SLFN12 (schlafen family member 12)
Description:
Ribonuclease which is part of an E2/17beta-estradiol-induced pro-apoptotic signaling pathway. E2 stabilizes the PDE3A/SLFN12 complex in the cytosol, promoting the dephosphorylation of SLFN12 and activating its pro-apoptotic ribosomal RNA/rRNA ribonuclease activity. This apoptotic pathway might be relevant in tissues with high concentration of E2 and be for instance involved in placenta remodeling. May play a role in cell differentiation.
Synonyms: FLJ10260; SLFN3
Tractability: Small molecule: a structure with a bound ligand is known. PROTAC: ubiquitination databases record sites on it; a small molecule that binds it is known.
Target class: Enzyme; Hydrolase
Gene: Protein-coding gene on chromosome 17 (35,409,347 to 35,433,475, reverse strand). Ensembl gene ENSG00000172123.
Subcellular location: Nucleus; Cytoplasm, cytosol
Gene Ontology:
Molecular function: protein binding; ribosome binding; RNA nuclease activity
Biological process: apoptotic signaling pathway; rRNA catabolic process
Cellular component: cytosol; nucleus
Genetic constraint (gnomAD): Loss-of-function variants: 24 observed, 27.58 expected, observed/expected ratio (o/e) 0.87, 90% interval 0.63 to 1.22. The upper end of that interval is the gene's LOEUF score, 1.22, which puts it in group 5 of 6, group 1 being the genes least tolerant of losing a copy. Missense variants: 631 observed, 674.5 expected, observed/expected ratio (o/e) 0.94, 90% interval 0.88 to 1. Synonymous variants: 252 observed, 243.24 expected, observed/expected ratio (o/e) 1.04, 90% interval 0.93 to 1.15.
Homologues: Orthologues: chimpanzee SLFN12 (99% identical), macaque SLFN12 (90% identical), mouse Slfn4 (43% identical), mouse Slfn3 (41% identical), rat Slfn4l1 (40% identical), mouse Slfn2 (33% identical), rat Slfn2 (32% identical), mouse Slfn1 (29% identical), rat Slfn1 (28% identical). Paralogues in human: SLFN12L (75% identical), SLFN5 (44% identical), SLFN14 (43% identical), SLFN13 (39% identical), SLFN11 (38% identical), SLFNL1 (9% identical).
Diseases named in the same sentence as SLFN12 in open-access papers:
SLFN12 is named in the same sentence as 39 diseases in open-access papers, as found by Europe PMC text mining. Sharing a sentence is not in itself a finding about the gene and the disease. The quoted sentences say what the papers report.
breast carcinoma (8 papers, 2020 to 2024). "Another interesting finding was the association of choline with a decreased risk of breast cancer only mediated by the hypomethylation of cg21697381, located in the open sea region of the SLFN12 promoter." (PMID 37630812, 2023). "Both GSEAs verified important function associations based on the significant changes in gene expression after the introduction of SLFN12 and identified potential pathways that merited future investigation, including several pathways associated with breast cancer." (PMID 36672349, 2023). "However, whether the SLFN12 gene is related to a reduced risk of breast cancer conferred by choline needs to be further investigated." (PMID 37630812, 2023). "For example, SLFN5 and SLFN12 exhibit positive feedback in breast cancer, while SLFN5, SLFN11, and SLFN13 all play roles in HIV-1 regulation." (PMID 39558948, 2024). "SLFN12 is also known to mediate the differentiation of intestinal epithelial cells, as well as prostate and breast cancer cells." (PMID 39558948, 2024). "Utilizing qPCR, we measured the RNA expression of eight genes from the SLFN12 signature gene set that were shown to be significantly up- or downregulated by RNA-seq and are known to be involved in breast cancer progression or regulation." (PMID 36672349, 2023). "Our analysis demonstrates that the SLFN12 gene signature predicts a better survival in breast cancer." (PMID 36672349, 2023). "Then, we used xenograft tumor bulk RNA-seq data to investigate pathways related to SLFN12 in breast cancer and used a statistical analysis to develop a gene signature." (PMID 36672349, 2023). "Unlike the observation with SLFN11, SLFN12 expression is correlated with endocrine therapy sensitivity in estrogen-positive breast cancer, as SLFN12 is one of the 60 differentially methylated region (DMR) genes in breast cancers with endocrine resistance." (PMID 34571887, 2021). "Our previously published work identified SLFN12 as modulating differentiation in intestinal epithelium, breast cancer, and prostate cancer." (PMID 32987632, 2020). "Schlafen 12 (SLFN12) is an intermediate human Schlafen that induces differentiation in enterocytes, prostate, and breast cancer." (PMID 32987632, 2020). "Therapies that would target SLFN12 and its corresponding gene signature could lead to a reduced tumor growth, an increased differentiation of breast cancer cells with luminal markers, and an increased survival of patients." (PMID 36672349, 2023). "However, the present results indicate that the SLFN12-associated gene signature appears to predict survival not only in TNBC but in all breast cancers and is more predictive than SLFN12 alone." (PMID 36672349, 2023). "This study sought to further investigate the role of SLFN12 in breast cancer." (PMID 36672349, 2023). "SLFN12 induces differentiation in enterocytes and breast cancer cells in 2D cultures." (PMID 36672349, 2023). "SLFN12 induces differentiation in the enterocyte, in prostate cancer, and in breast cancer." (PMID 32987632, 2020). "SLFN12 signature genes could be part of the network that explain severity of triple negative breast cancer in African American and might play a role in future design of personalized therapy for patients with breast cancer." (PMID 36672349, 2023). "Furthermore, this SLFN12 gene signature could serve as a prognostic predictor of breast cancer severity and could help to develop personalized targeted therapy for African Americans or patients of other races." (PMID 36672349, 2023). "We used Taqman qPCR to investigate the correlation between the differential methylation of IRF6, SLFN12, and RNF39 with their gene expression at baseline and after the first cycle of DOX chemotherapy in PBMCs of breast cancer patients." (PMID 34944912, 2021). "Human SLFN5, SLFN11, SLFN12, SLFN13, and SLFN14 are all downregulated in breast cancer, lung squamous carcinoma, prostate cancer, and rectal carcinoma." (PMID 34571887, 2021).
breast carcinoma (continued). "Instead, SLFN12 acted through inhibiting the translation of c-myc protein, similar to how SLFN12 modulates the expression of ZEB1 in breast cancer." (PMID 32987632, 2020). "CK-5 and P63 were picked because they are both markers of squamous cell carcinoma, and SFTPC, SCGB1A1, and HOPX are markers of LUAD, while CDH1 was picked because SLFN12 has been demonstrated to modulate CDH1 expression in prostate and breast cancers." (PMID 32987632, 2020). "We have previously reported that SLFN12 itself is predictive of survival in triple-negative breast cancer but not in other breast cancers." (PMID 36672349, 2023). "Furthermore, Slfn12 regulates ZEB1 and Slug protein conversely to the mRNA in breast cancer cells and c-Myc in lung adenocarcinoma cells." (PMID 34710177, 2021).
triple-negative breast carcinoma (7 papers, 2021 to 2025). An invasive breast carcinoma which is negative for expression of estrogen receptor (ER), progesterone receptor (PR), and human epidermal growth factor receptor 2 (HER2). "The Schlafen (SLFN) gene family, especially SLFN12, is essential for regulating the biological processes associated with triple-negative breast cancer (TNBC)." (PMID 39558948, 2024). "SLFN12 has previously been associated with various diseases and pathways, including lung adenocarcinoma, triple-negative breast cancer, prostate cancer, T cell activation, and human enterocytic differentiation." (PMID 36672349, 2023). "Reactivating SLFN11 via HDAC inhibitors restores cancer cell sensitivity to DNA-damaging agents, while SLFN12 influences immune regulation and chemotherapy response in triple-negative breast cancer." (PMID 41303540, 2025). "SLFN12 stimulates differentiation in enterocytes and prostate cancer cells, and its overexpression inhibits prostate cancer, triple-negative breast cancer (TNBC), and lung adenocarcinoma cell proliferation." (PMID 39594803, 2024). "Background/Objectives: Schlafen12 (SLFN12) is an intermediate human Schlafen protein shown to correlate with survivability in triple-negative breast cancer (TNBC)." (PMID 39594803, 2024). "Schlafen 12 (SLFN12) is a protein-coding gene that has a reduced expression in human triple-negative breast cancer (TNBC) tumors and correlates with survival." (PMID 36672349, 2023). "The over-expression of SLFN12 can sensitize triple-negative breast cancer cells to chemotherapy drugs and radiotherapy." (PMID 37630812, 2023). "The Schlafen 12 (SLFN12) protein regulates triple-negative breast cancer (TNBC) growth, differentiation, and proliferation." (PMID 36672349, 2023). "Expression of both the long SLFN5, which targets to the nucleus, and the intermediate SLFN12, which targets to the cytosol, is correlated with survival, tumor growth, and metastasis in triple negative breast cancer." (PMID 34571887, 2021). "In addition, recent work has also investigated the role of SLFN12 in regulating other SLFN family members in the context of triple-negative breast cancer (TNBC) and chemotherapy response." (PMID 41303540, 2025). "In contrast, SLFN12 inhibits ZEB1 translation without transcriptional inhibition, induces CD44+/CD24- stem cell differentiation, and reduces the proliferation of triple negative breast cancer cells but not the ER+/PR+ MCF7 cells." (PMID 34571887, 2021).
lung adenocarcinoma (4 papers, 2020 to 2024). A carcinoma that arises from the lung and is characterized by the presence of malignant glandular epithelial cells. "TNBC and lung adenocarcinoma patients have longer survival when SLFN12 is expressed at higher levels than tumors expressing less SLFN12." (PMID 39594803, 2024). "Our RT-qPCR results show that overexpression of SLFN12 significantly increased TTF-1 mRNA levels in two of the three lung adenocarcinoma cells (HCC827 and H1975)." (PMID 32987632, 2020). "As we knew that SLFN12 alters cell differentiation, we initially sought an explanation for the apparent protective implications of high SLFN12 expression in lung adenocarcinoma by examining the expression of several important differentiation markers." (PMID 32987632, 2020). "In conclusion, our results indicate that SLFN12 plays a favorable prognostic role in lung adenocarcinoma at least in part by modulating c-myc expression." (PMID 32987632, 2020). "Because SLFN12 has been implicated in the regulation of differentiation in other epithelial tissues, we next sought to examine the effect of exogenous SLFN12 overexpression on a set of differentiation markers in a panel of lung adenocarcinoma and squamous cell carcinoma cell lines." (PMID 32987632, 2020). "On one hand, our data raise the possibility that lung adenocarcinomas with higher expression of SLFN12 might behave in a less aggressive fashion, and thus might be amenable to less aggressive cytotoxic regimen." (PMID 32987632, 2020). "Our analysis using the publicly available km-plotter tool of gene expression profiles in a cohort of patients with non-small cell lung cancer showed that higher SLFN12 expression correlated with better survival in patients with lung adenocarcinoma (hazard ratio = 0.59, n = 719, p-value < 0.0001)." (PMID 32987632, 2020). "Thus, obtaining similar results implicating SLFN12 in the prognosis of human lung adenocarcinoma from both datasets validates and adds to the rigor of our conclusion that SLFN12 is prognostically important for these tumors." (PMID 32987632, 2020). "Moreover, bioinformatics analysis of datasets in lung adenocarcinoma identifies the correlation of SLFN12 with other known lung adenocarcinoma markers like KRT7, Napsin A, and TTF-1." (PMID 32987632, 2020). "On the other hand, future studies may develop drugs targeted at activating an SLFN12-mediated pathway that might be useful in lung adenocarcinomas that express low levels of SLFN12." (PMID 32987632, 2020). "This molecule might be useful to treat lung adenocarcinomas that express high levels of SLFN12, but this must await further study." (PMID 32987632, 2020). "In vitro, overexpressing SLFN12 in lung adenocarcinoma cells reduces proliferation by inhibiting c-myc translation, with no similar effect on c-myc or cell proliferation in lung adenocarcinoma cells, demonstrating a specific SLFN12 effect in one distinct subtype of lung cancer (lung adenocarcinoma)." (PMID 34571887, 2021). "We then adenovirally overexpressed SLFN12 (AdSLFN12) in HCC827, H23, and H1975 cells to model lung adenocarcinoma (LUAD), and in H2170 and HTB-182 cells representing lung squamous cell carcinoma (LUSC)." (PMID 32987632, 2020). "SLFN12 correlates with survival in patients with lung adenocarcinoma but not in patients with lung squamous cell carcinoma." (PMID 34571887, 2021). "Our results not only indicate the prognostic significance of SLFN12 in LUAD, but also suggest that SLFN12 and its downstream effectors may be useful targets for the future design of precision medicine for adenocarcinoma of the lung." (PMID 32987632, 2020). "Our analysis demonstrated that high versus low SLFN12 expression is able to classify the lung adenocarcinoma, but not squamous cell carcinoma patients into good versus poor survival." (PMID 32987632, 2020). "The prognostic implications of SLFN12 expression appear exclusive to lung adenocarcinoma and do not apply to squamous cell carcinoma." (PMID 32987632, 2020).
lung adenocarcinoma (continued). "Although SLFN12 was previously reported to act through modulating proteasomal and USP14 and USCHL5 deubiquitylase activity, this did not appear to be the case in lung adenocarcinoma cells." (PMID 32987632, 2020).
multiple sclerosis (4 papers, 2018 to 2025). A progressive autoimmune disorder affecting the central nervous system resulting in demyelination. "In conclusion, SLFN12 seems to be linked with autoimmune diseases such as multiple sclerosis." (PMID 38832156, 2024). "A study involving isolated CD4+ and CD8+ T cells from multiple sclerosis (MS) patients indicated regions of hypermethylation in SLFN12 owing to an overall decrease in SLFN12 expression in whole blood samples of multiple sclerosis patients when compared to controls." (PMID 41303540, 2025). "Beyond oncology, altered SLFN12 methylation in autoimmune diseases such as multiple sclerosis and Hashimoto’s thyroiditis highlights its broader role in immune homeostasis, where methylation shifts may drive either immune suppression or hyperactivation." (PMID 41303540, 2025). "Evidence suggests elevated SLFN12 methylation levels in CD4+ and CD8+ T cells in the peripheral blood of patients with multiple sclerosis, a chronic inflammatory disease of the central nervous system." (PMID 38075038, 2023).
glioblastoma (3 papers, 2021 to 2025). The most malignant astrocytic tumor (WHO grade IV). "PDE3A and SLFN12 expression levels were measured in glioblastoma cell lines, the Cancer Genome Atlas (TCGA) tumor samples, and tumor neurospheres." (PMID 39166256, 2024). "Taken together, our work identifies velcrins as a novel therapeutic class with promising preclinical activity against glioblastomas with elevated SLFN12 and PDE3A expression." (PMID 39166256, 2024). "Based on previous work in solid tumors such as glioblastoma, only PDE3A and SLFN12 are considered as biomarkers for treatment with velcrins." (PMID 41150877, 2025). "Tumors with the highest PDE3A and SLFN12 expression levels include IDH wild-type low-grade gliomas and glioblastomas." (PMID 39166256, 2024). "Lastly, we observed in vivo sensitivity to 2 velcrin compounds in subcutaneous glioblastoma PDX models with high PDE3A and SLFN12 expression." (PMID 39166256, 2024). "In glioblastoma multiforme (GBM), high levels of all human Schlafens (SLFN5, SLFN11, SLFN12, and SLFN13) are correlated with shorter overall survival of patients." (PMID 34571887, 2021). "Additionally, we demonstrate the preclinical efficacy of BAY 2666605 and BRD3800 in glioblastomas with high expression of PDE3A and SLFN12 in vitro and in vivo, in both cellular and patient-derived glioblastoma models." (PMID 39166256, 2024).
glioma (3 papers, 2023 to 2024). A benign or malignant brain and spinal cord tumor that arises from glial cells (astrocytes, oligodendrocytes, ependymal cells). "Our results indicate that elevated SLFN12 expression is associated with worse overall survival across various glioma cohorts." (PMID 39740094, 2024). "The SLFN12 biomarker may have clinical significance as evidenced by its decreased susceptibility to other chemotherapies, like gemcitabine and cisplatin, which are occasionally included in salvage or combination regimens for gliomas." (PMID 39740094, 2024). "Additional laboratory experiments confirmed the role of SLFN12 in promoting glioma cell proliferation, migration and macrophage recruitment." (PMID 39740094, 2024). "We show that high SLFN12 expression significantly correlates with poorer overall survival in multiple independent glioma cohorts from two databases." (PMID 39740094, 2024). "Our findings demonstrate that the level of the Schlafen Family Member 12 (SLFN12) is a strong and independent predictor of immunotherapy response in gliomas." (PMID 39740094, 2024). "In summary, this study identifies SLFN12 as a novel biomarker for predicting immunotherapy response in glioma patients, offering new insights for precision immunotherapy approaches." (PMID 39740094, 2024). "Further investigation into these potential mechanisms will be essential for understanding the role of SLFN12 in macrophage activity and its implications for glioma immunotherapy responses." (PMID 39740094, 2024). "In conclusion, our study has identified SLFN12 as a novel predictive biomarker for response to anti‐PD‐1 immunotherapy in glioma patients." (PMID 39740094, 2024). "Further mechanistic investigations and prospective clinical validation studies are warranted to fully elucidate the role of SLFN12 in glioma immunobiology and its potential as a therapeutic target." (PMID 39740094, 2024). "Our findings demonstrate that expression of the SLFN12, as determined by our comprehensive analyses, is a strong and independent predictor of immunotherapy response in gliomas." (PMID 39740094, 2024). "The high SLFN12 group had a significantly shortened survival time in the TCGA glioma dataset." (PMID 39740094, 2024). "Our in vitro experiments demonstrating the impact of SLFN12 silencing on glioma cell proliferation, migration and macrophage recruitment provide preliminary evidence supporting this hypothesis." (PMID 39740094, 2024). "This study's prognostic value of SLFN12 expression in glioma is a key finding." (PMID 39740094, 2024). "Glioma cells with high SLFN12 expression may be more resistant to various chemotherapeutic drugs, as indicated by the higher IC50 values showing decreased drug sensitivity." (PMID 39740094, 2024). "The high SLFN12 group had significantly shortened survival times in different glioma datasets." (PMID 39740094, 2024).